ATRX (ATRX chromatin remodeler)
Description:
Involved in transcriptional regulation and chromatin remodeling. Facilitates DNA replication in multiple cellular environments and is required for efficient replication of a subset of genomic loci. Binds to DNA tandem repeat sequences in both telomeres and euchromatin and in vitro binds DNA quadruplex structures. May help stabilizing G-rich regions into regular chromatin structures by remodeling G4 DNA and incorporating H3.3-containing nucleosomes. Catalytic component of the chromatin remodeling complex ATRX:DAXX which has ATP-dependent DNA translocase activity and catalyzes the replication-independent deposition of histone H3.3 in pericentric DNA repeats outside S-phase and telomeres, and the in vitro remodeling of H3.3-containing nucleosomes. Its heterochromatin targeting is proposed to involve a combinatorial readout of histone H3 modifications (specifically methylation states of H3K9 and H3K4) and association with CBX5. Involved in maintaining telomere structural integrity in embryonic stem cells which probably implies recruitment of CBX5 to telomeres. Reports on the involvement in transcriptional regulation of telomeric repeat-containing RNA (TERRA) are conflicting; according to a report, it is not sufficient to decrease chromatin condensation at telomeres nor to increase expression of telomeric RNA in fibroblasts. May be involved in telomere maintenance via recombination in ALT (alternative lengthening of telomeres) cell lines. Acts as a negative regulator of chromatin incorporation of transcriptionally repressive histone MACROH2A1, particularily at telomeres and the alpha-globin cluster in erythroleukemic cells. Participates in the allele-specific gene expression at the imprinted IGF2/H19 gene locus. On the maternal allele, required for the chromatin occupancy of SMC1 and CTCF within the H19 imprinting control region (ICR) and involved in establishment of histone tails modifications in the ICR. May be involved in brain development and facial morphogenesis. Binds to zinc-finger coding genes with atypical chromatin signatures and regulates its H3K9me3 levels. Forms a complex with ZNF274, TRIM28 and SETDB1 to facilitate the deposition and maintenance of H3K9me3 at the 3' exons of zinc-finger genes.
Synonyms: XNP; RAD54L; XH2; JMS; MRX52; RAD54; ZNF-HX
Tractability: PROTAC: UniProt records ubiquitination sites on it; ubiquitination databases record sites on it; its protein half-life has been measured.
Gene: Protein-coding gene on chromosome X (77,504,880 to 77,786,233, reverse strand). Ensembl gene ENSG00000085224.
Subcellular location: Nucleus; Chromosome, telomere; Nucleus, PML body
Subcellular location (Human Protein Atlas): Nuclear bodies
Pathways (Reactome):
Disease: Defective Inhibition of DNA Recombination at Telomere Due to ATRX Mutations; Defective Inhibition of DNA Recombination at Telomere Due to DAXX Mutations
Cell Cycle: Inhibition of DNA recombination at telomere
Gene Ontology:
Molecular function: ATP-dependent chromatin remodeler activity; chromatin binding; chromo shadow domain binding; histone binding; histone H3K9me2/3 reader activity; protein binding; chromatin DNA binding; ATP binding; ATP hydrolysis activity
Biological process: chromatin organization; chromatin remodeling; negative regulation of maintenance of mitotic sister chromatid cohesion, telomeric; positive regulation of transcription by RNA polymerase II; subtelomeric heterochromatin formation; cellular response to hydroxyurea; positive regulation of nuclear cell cycle DNA replication; positive regulation of telomere maintenance; protein localization to chromosome, telomeric region; regulation of DNA-templated transcription; replication fork processing; regulation of cell cycle process; regulation of chromosome organization
Cellular component: chromosome, subtelomeric region; nuclear body; chromosome, telomeric region; heterochromatin; nucleoplasm; nucleus; pericentric heterochromatin; PML body; condensed chromosome, centromeric region; nuclear chromosome
Gene-disease validity (ClinGen):
ClinGen rates the evidence that ATRX causes each of these diseases.
ATR-X-related syndrome (X-linked): Definitive. A X-linked intellectual disability characterized by distinctive craniofacial features, genital anomalies, hypotonia, and mild-to-profound developmental delay/intellectual disability.
Cancer hallmarks: genome instability and mutations (suppresses)
Homologues: Orthologues: chimpanzee ATRX (99% identical), macaque ATRX (99% identical), pig ATRX (93% identical), guinea pig ATRX (90% identical), rabbit ATRX (90% identical), rat Atrx (85% identical), mouse Atrx (84% identical), tropical clawed frog atrx (58% identical), zebrafish atrx (47% identical), zebrafish atrxl (31% identical), Caenorhabditis elegans xnp-1 (21% identical), Drosophila melanogaster XNP (21% identical). Paralogues in human: RAD54L2 (12% identical), CHD7 (11% identical), EP400 (11% identical), CHD4 (11% identical), CHD3 (11% identical), CHD5 (11% identical), CHD9 (11% identical), SMARCA4 (11% identical), SMARCA2 (11% identical), SRCAP (10% identical), CHD2 (10% identical), ERCC6 (10% identical), and 18 more.
Diseases named in the same sentence as ATRX in open-access papers:
ATRX is named in the same sentence as 270 diseases in open-access papers, as found by Europe PMC text mining. Sharing a sentence is not in itself a finding about the gene and the disease. The quoted sentences say what the papers report.
glioma (451 papers, 2012 to 2026). A benign or malignant brain and spinal cord tumor that arises from glial cells (astrocytes, oligodendrocytes, ependymal cells). "This case is notable because 1p/19q codeletion and ATRX loss are typically mutually exclusive in gliomas." (PMID 41596318, 2026). "The (inactive) mutation of ATRX disrupts the gene regulation of glioma chromatin remodeling, promoting the stabilization of glioma cells." (PMID 40264576, 2025). "In cell line experiments, radiotherapy and temozolomide chemotherapy‐induced high expression of PD‐L1 in IDH‐mutant glioma cells with ATRX mutations, promoting tumor immune escape." (PMID 40264576, 2025). "For functional testing, we employed the TeloDIAG, a combined assay that integrates telomere content quantification with CC detection, thereby providing a robust evaluation of the functional consequences of ATRX mutations for clinical glioma diagnosis." (PMID 41422096, 2025). "Although no previous study has investigated the relationship between ATRX status and FDG uptake, ATRX function loss or mutations mainly occur in low-grade gliomas and are rare in high grade gliomas." (PMID 40786409, 2025). "DRG2 was previously shown to be downregulated in IDH1-mutant gliomas, where ATRX mutations are common." (PMID 40775769, 2025). "Gliomas with ATRX mutation commonly also present IDH mutation and show a better prognosis as compared to ATRX-wild-type IDH-mutant gliomas." (PMID 40870498, 2025). "ATRX dysfunction is commonly associated with glioma mutations, particularly in lower-grade gliomas and secondary GBM, and is often linked to altered telomere maintenance mechanisms." (PMID 40282990, 2025). "While some studies indicate its tumor-suppressive properties—via inhibition of miR-21 through NF-κB modulation—others show that its overexpression correlates with poor outcomes, particularly in ATRX-deficient gliomas." (PMID 40710366, 2025). "This alteration is strongly associated with IDH mutations and is almost mutually exclusive with ATRX mutations, reinforcing its role as a key molecular marker in glioma classification." (PMID 40628732, 2025). "Through a focus on glioma tumours, we have identified that generation of excessive ROS can act as a potent and essential driving factor in ATRX-deficient malignant cells." (PMID 39921567, 2025). "This cascade of events ultimately initiates an immune-tolerance-promoting process in ATRX-mutated gliomas." (PMID 40927709, 2025). "Despite analyses of four samples identifying ATRX mutations as a significant molecular factor in lower-grade gliomas, ALT activation has been associated with ATRX deficiency in only 14–35% of high-grade pediatric gliomas." (PMID 40362411, 2025). "Recent studies have shown that ATRX mutations have significantly different effects on the biological function and disease prognosis of glioma cells in the context of different IDH mutation statuses." (PMID 40264576, 2025). "These tumors exhibited significantly elevated TL ratios compared to other genetic subtypes, suggesting a critical role for ATRX mutations in telomere length regulation and maintenance in gliomas." (PMID 40362411, 2025). "Here, we demonstrate that excessive cellular reactive oxygen species (ROS) is an important causative factor in the evolution of ALT-telomere maintenance in ATRX-deficient glioma." (PMID 39921567, 2025).
glioma (continued). "In vivo studies demonstrated that SIRT2 inhibitors slowed down the growth of ATRX-deficient glioma xenografts and also induced senescence in these tumors, suggesting a potential therapeutic strategy for treating this aggressive cancer type." (PMID 40710366, 2025). "ATRX loss is also frequently observed in H3.3-mutated gliomas (G34R/V and K27M), including nearly 100% of hemispheric G34R/V-mutant gliomas and approximately 30% of midline diffuse gliomas." (PMID 41422096, 2025). "After removing duplicates and filtering by diagnosis according to the WHO 2021 criteria, we selected 539 glioma samples with ATRX variants identified by NGS." (PMID 41422096, 2025). "ATRX is frequently mutated in GBM, and CRISPR-Cas9 ATRX knockout suppresses cell proliferation, invasion, and vasculogenic mimicry in glioma cells, resulting in increased sensitivity to TMZ by enhancing TMZ-induced DNA damage and apoptosis." (PMID 40868217, 2025). "In 2011, ATRX mutations were found to exist in central nervous system tumors, and subsequent studies confirmed that ATRX mutations primarily occur in diffuse astrocytomas." (PMID 40103938, 2025). "Recent work has shown that mutant IDH1 cooperates with ATRX loss in promoting the alternative lengthening of telomere (ALT) phenotype in gliomas, highlighting mechanisms of pathogenic interplay between the two molecular abnormalities." (PMID 38272925, 2024). "Patients with ATRX-mutated gliomas, especially in the context of concurrent IDH mutations, tend to have longer survival outcomes compared to patients with ATRX-wild-type glioblastomas." (PMID 39767571, 2024). "Taken together, these findings strongly suggest that the indolent growth of ATRX-deficient glioma models is largely attributable to immune microenvironmental effects." (PMID 38272925, 2024). "Mutations in ATRX constitute the most prevalent genetic abnormalities in gliomas, and interestingly, ATRX alterations are associated with favorable outcomes." (PMID 38279330, 2024). "ATRX loss is frequently used to diagnose gliomas, loss of H3K27me3 is employed to identify specific subtypes of diffuse midline gliomas, and INI1 loss is characteristic of atypical teratoid/rhabdoid tumors." (PMID 39409918, 2024). "Suggesting a connection between ATRX loss and immune-modulatory behavior, pro-inflammatory gene expression profiles are enriched among ATRX-mutant low-grade gliomas." (PMID 38272925, 2024). "ATRX is also seen mutated in gliomas but rarely in other cancer types, suggesting that the effects of ATRX loss are different based on the cell/tissue of origin." (PMID 38473300, 2024). "In cases of IDH‐mutant gliomas with intact 1p/19q or loss of ATRX as a surrogate in a child, adolescent, or young adult, a heightened level of suspicion is warranted, particularly if the histology exhibits high‐grade features." (PMID 38339779, 2024). "The mutation status of the Alpha-thalassemia X-linked mutant retardation syndrome (ATRX) was incorporated into the glioma diagnostic algorithm in 2016." (PMID 38898533, 2024). "We found that differences in allograft growth between ATRX-intact and ATRX-deficient glioma were much less apparent in nude hosts compared to C57BL/6 immunocompetent hosts." (PMID 38272925, 2024). "The ATRX mutations occurs at high frequencies in both low-grade gliomas (71%) and secondary GBM (57%)." (PMID 38898533, 2024). "ATRX inactivation occurs often in IDH-mutant gliomas and has been associated with immune dysfunction." (PMID 38272925, 2024). "Genomic profiling of ATRX-deficient adult high-grade gliomas revealed the genetic characteristics of homologous recombination repair." (PMID 38898533, 2024). "Mutations in the ATRX gene are frequently observed in certain types of gliomas, where they are associated with the alternative lengthening of telomeres phenotype, genomic instability, and altered epigenetic landscapes." (PMID 38542090, 2024).
glioma (continued). "In the present study, the ATRX mutation rate in patients with glioma was obtained from The Cancer Genome Atlas, while its expression analyzed using bioinformatics." (PMID 38898533, 2024). "This summary highlights the impact of ATRX mutations on gliomas, neuroblastomas, pancreatic neuroendocrine tumors, and osteosarcomas." (PMID 39479502, 2024). "Taken together, these findings mirror those of human gliomas, where ATRX deficiency was associated with immune cell infiltration and pro-inflammatory signaling." (PMID 38272925, 2024). "Radiomics models have been developed to predict genetic features like MGMT methylation and EGFR-A289V mutations in high-grade gliomas and ATRX mutations in lower-grade gliomas (LGGs)." (PMID 38927583, 2024). "In the TCGA glioma datasets, approximately 21% of the samples exhibited ATRX mutations, with truncating mutations and deletions most commonly occurring." (PMID 39479502, 2024). "ATRX mutations substantially contribute to the pathogenesis of ATRX syndrome and are frequently detected in gliomas and many other cancers." (PMID 39479502, 2024). "ATRX mutations are also associated with other favorable prognostic markers, such as 1p/19q codeletions in lower-grade gliomas, further contributing to better outcomes in this subgroup." (PMID 39767571, 2024). "ATRX-deficient glioma cells are sensitive to dsRNA-based innate immune agonism and exhibit impaired lethality and increased T-cell infiltration in vivo." (PMID 38272925, 2024). "We observed an induction in RIG-I and MDA5 in both our human and mouse ATRX-deficient glioma models, indicative of enhanced sensitivity to dsRNA." (PMID 38272925, 2024). "To determine the extent to which ATRX-deficient glioma models remain sensitive to dsRNA immune agonism in the context of IDH1R132H, we subjected our isogenic CT2A lines to HMW poly(I:C), monitoring levels of key pathway constituents." (PMID 38272925, 2024). "IDH-mutant gliomas are also often associated with other favorable biomarkers, such as ATRX mutations and 1p/19q codeletions, further contributing to better outcomes." (PMID 39767571, 2024). "In glioma, loss of ATRX results in genomic instability and impaired NHEJ repair of double-strand breaks, making it more responsive to DNA damaging therapies such as radiation." (PMID 39315270, 2024). "ATRX loss is often correlated with poor prognosis, increased tumor aggressiveness, and a specific molecular subtype of glioma." (PMID 38542090, 2024). "To determine if ATRX mutations associate with inflammatory signaling pathways in glioma patients, we first performed gene set enrichment analysis (GSEA) on TCGA bulk RNAseq data from IDH1-mutant low-grade gliomas (LGG)." (PMID 38272925, 2024). "Researchers utilizing the information from the CGGA database have employed the ESTIMATE algorithm to evaluate the stromal and immune scores of ATRX-mutated versus wild-type (ATRX-wt) glioma tissues." (PMID 39513108, 2024). "In this investigation, we leverage multiple glioma models to demonstrate that ATRX deficiency leads to increased innate immune signaling and cytokine secretion in response to dsRNA-based innate immune agonism." (PMID 38272925, 2024). "Studies indicate that the median overall survival (OS) for patients with ATRX mutations in the context of IDH-mutant gliomas can extend beyond 24–36 months, significantly longer than the 12–15 months commonly observed in primary (IDH wild-type) glioblastomas." (PMID 39767571, 2024).